IL1B (interleukin 1 beta)
Diseases named in the same sentence as IL1B in open-access papers (continued):
Sharing a sentence is not in itself a finding about the gene and the disease.
endometriosis (continued). "The aberrant control of IL-1β activity can enhance the risk of the adhesion and growth of the ectopic endometrium, leading to the development of endometriosis." (PMID 36555618, 2022). "There is still a scientific debate regarding the association of different IL-1β SNPs and endometriosis." (PMID 36028805, 2022). "When we analyzed the carriage rate of IL1B*2 allele (*1*2 + *2*2), we found a statistically significant difference between women with endometriosis stage IV and the CTR group (p = 0.041)." (PMID 36028805, 2022). "Inflammatory factors, such as IL-1β and corticotropin releasing hormone, play a role in pain associated with deep infiltrating endometriosis, a disorder that is physiologically and histologically similar to adenomyosis." (PMID 35773139, 2022). "In this respect, a nested case–control study revealed that plasma IL-1β levels were positively associated with an increased risk to develop endometriosis." (PMID 32063886, 2019). "IL-1R2, the decoy form of the receptor has also been identified as deficient in human endometriosis, which is thought to be an IL-1β-induced pathology." (PMID 20066156, 2010). "For instance, measuring the number of imDC or even the cytokines produced by the DC, like IL-1β, IL-6, and IL-10, in the peritoneal fluid of patients with endometriosis might serve as a diagnostic tool." (PMID 40747182, 2025). "This study provides integrative evidence that triclosan may promote endometriosis through immune and growth-related pathways, with IL1B identified as a causal mediator." (PMID 41239476, 2025). "MR analysis was performed to evaluate causality between IL1B expression and endometriosis risk." (PMID 41239476, 2025). "Studies have shown that women carrying specific IL1A and IL1B alleles may have an increased risk of developing endometriosis due to higher IL-1 production." (PMID 39767772, 2024). "In this study, we present the intra-individual heterogeneity in PGP9.5 nerve bundle density and associated biomarkers of neuroproliferation (NGF, IL-1β), amongst patients who had all three anatomic subtypes of endometriosis at surgery and where at least two subtypes were available for analysis." (PMID 38785989, 2024). "Notably, IL-1β promotes local neurogenesis and increases nerve density around endometriosis and endometriosis-associated pain." (PMID 39141428, 2024). "Defective mechanisms involved in the control of local IL‐1β activity may enhance susceptibility for the adhesion and growth of the ectopic endometrium and it leads to the development of endometriosis." (PMID 37143676, 2023). "IL-1β as an inflammatory factor could stimulate nerve growth factor expression in endometriosis directly, thus it is associated with local neurogenesis adjacent to endometriosis lesions and so severe deep dyspareunia." (PMID 37416064, 2023). "This may be related to the main pathogenesis of endometriosis causing a chronic inflammatory environment with increased levels of proinflammatory cytokines such as IL-1β, IL-6, and tumor necrosis factor-α." (PMID 37629431, 2023). "This could lead to an insufficient production of IL-1Ra protein or to an overproduction of IL-1β in response to immune and/or inflammatory stimuli, explaining why this allele could influence an individual’s susceptibility to endometriosis." (PMID 36028805, 2022). "Although the IL1B*2-allele heterozygote genotype frequency was similar between groups, we only found a statistically significant difference between women with stage IV endometriosis and the CTR group (p = 0.044)." (PMID 36028805, 2022). "In addition, the expression of IL-1β, which has been associated with the risk of endometriosis appears to depend on the stage of the disease and stimulates the upregulation of biomolecules that induce pain." (PMID 33435569, 2021).
endometriosis (continued). "It is possible, however, that expression of this chemokine by endometriotic stromal and epithelial cells may be induced and increased by proinflammatory cytokines involved in endometriosis-associated inflammation, e.g., IL-1b, TNF, and IL-17." (PMID 34501240, 2021). "TNF-α and IL-1β are up-regulated in the peritoneal fluid (PF) of women with Endometriosis causing a decrease in the expression of progesterone receptor type B (PRB) mRNA in endometrial stromal cells isolated from women with Endometriosis." (PMID 33354460, 2020). "The imbalance between IL-1α, pro-IL-1β, sIL-1R2, and sIL-1RAcP in the PF and serum of endometriosis patents may be linked to the ability to transform acute inflammation into a chronic one." (PMID 32145751, 2020). "The abnormal presence of intrafollicular IL-1β and IL-6 could affect the follicular biology of endometriosis patients because low intrafollicular IL-6 is associated with a higher pregnancy rate." (PMID 30104541, 2018). "One could hypothesize that after retrograde menstruation; deficiency of IL-RA coupled to over expression of IL-1β in women with endometriosis may lead to increased stimulation of immune cells, endometrial and ectopically implanted endometrial cells." (PMID 20181040, 2010). "The endometriosis cases with pain with bowel movements were less likely to have IL-1β levels that were above the lower limit of detection or higher compared to those without pain with bowel movements." (PMID 40508188, 2025). "Genes associated with endometriosis risk are highly expressed in M2 macrophages, particularly ligands IL1A and IL1B." (PMID 40938538, 2025). "This approach enhances causal inference and reduces potential confounding, thereby strengthening the evidence for IL1B’s involvement in endometriosis." (PMID 41239476, 2025). "Immunological Impact: Research on animals demonstrates that antibiotic treatment lowers levels of important inflammatory cytokines, including IL-1β, IL-6, and TNF-α, which are associated with endometriosis development." (PMID 40725782, 2025). "In the context of endometriosis, C5a stimulates peritoneal macrophages to produce pro-inflammatory cytokines IL-1β, IL-6, TNF-α, and IL-8, enhancing the cytokine imbalance characteristic of this disease (Section 4)." (PMID 41488658, 2025). "Patients with endometriosis show elevated concentrations in peritoneal fluid of key cytokines supporting cell-mediated immunity and inflammation: IL-1β, IL-6, and TNF-α." (PMID 41488658, 2025). "Prostaglandin E2, TNFα, NGF, RANTES, IL-8, and IL-1β are elevated within the peritoneal fluid of endometriosis patients." (PMID 40508002, 2025). "Interleukin (IL)-1β has consistently been reported at higher levels in the peritoneal fluid of women with endometriosis and pelvic pain compared to that of control women." (PMID 40508188, 2025). "Although pharmacological interventions targeting cytokines have not undergone analysis in clinical trials, epidemiological data concerning the efficacy of various inhibitors of TNFα and IL-1β concerning endometriosis and fertility must be examined." (PMID 40508002, 2025). "Women with endometriosis have elevated levels of key pro-inflammatory cytokines, i.e., IL-1β, IL-6, and TNF-α." (PMID 39859551, 2025). "In endometriosis, M1 macrophages attract immune cells to ectopic lesions by releasing pro‐inflammatory factors (such as IL‐1β and TNF‐α) in the early stages, triggering inflammatory responses and inhibiting lesion growth." (PMID 40739711, 2025). "Together, these findings support a model where triclosan exposure activates IL1B and growth factor pathways, potentially exacerbating endometriosis through immune modulation, angiogenesis, and estrogen sensitivity." (PMID 41239476, 2025). "TNF-α, together with IL1-β, was shown to stimulate IL-8 production, contributing to the inflammatory milieu and pain in endometriosis." (PMID 40724945, 2025).
endometriosis (continued). "Among the hub genes, IL1B stands out due to its well-documented role in endometriosis-related inflammation." (PMID 41239476, 2025). "Studies have shown that patients with endometriosis develop high levels of IL-1β, IL-8, IL-6, and other pro-inflammatory factors." (PMID 40761347, 2025). "IL-17 has been shown to promote the production of other proinflammatory cytokines, such as IL-1α and IL-1β, involved in the pathogenesis of endometriosis." (PMID 39061077, 2024). "Animal studies have demonstrated that gut microbiome plays a crucial pro-inflammatory role in the progression of endometriosis and results in higher levels of IL-1β, TNF-α, IL-6, and TGF-β1 and an increase in macrophages at the lesion site." (PMID 38627726, 2024). "Alpha-lipoic acid has been shown to prevent endometriosis by preventing the NLRP3-mediated release of IL-1β and IL-18." (PMID 39769450, 2024). "Increased IL-1β has been found in peritoneal fluids and lesions from women with endometriosis and pelvic pain." (PMID 39141428, 2024). "The dysregulated cytotoxicity of peritoneal NK cells in endometriosis can be attributed to various cytokines (IL-6, IL-8, IL-1β, IFN-γ, and TNF-α) and inhibitory factors present in both serum and peritoneal fluid." (PMID 39309679, 2024). "TET3 acts as a positive regulator for the expression of proinflammatory genes, such as IL-6 and IL-1β, both of which play well-documented roles in the pathology of endometriosis." (PMID 39141428, 2024). "Several serum cytokines such as interleukins (IL) IL1β, IL-5, IL-6, IL-7 and IL-12 are involved, and their levels were found to be altered in endometriosis as compared to in healthy women." (PMID 39309679, 2024). "Recently, studies have begun to explore the IL-1β-NGF pathway to pain in relation to endometriosis phenotypes." (PMID 38785989, 2024). "Significant decreases in serum levels of IL-1β and TNFα were observed in women with endometriosis treated with ATX for 12 weeks." (PMID 39199150, 2024). "In the current work, we provide critical mechanistic insights into TET3-mediated regulation of IL-1β and IL-6, 2 key cytokines with well-established roles in endometriosis." (PMID 39141428, 2024). "Elevated IL-1β and IL-18 levels are seen in follicular fluid of endometriosis patients undergoing ovarian stimulation." (PMID 39769450, 2024). "The cytokines IL-1β and IL-6 are known to play important roles in the pathophysiology of endometriosis." (PMID 39141428, 2024). "The response to LPS, marked by a substantial increase in IL1B expression, was attenuated when macrophages had been treated with endometriosis sEVs, but the magnitude of this reduction was moderate." (PMID 39062452, 2024). "TNF-α and IL-1β mainly secreted by macrophages are highly expressed in the peritoneal fluid of endometriosis patients which can lead to peripheral nerve hypersensitivity and hyperalgesia." (PMID 38505548, 2024). "One study demonstrated that the number of macrophages, monocytes, and cytokines in the peritoneal fluid of women with endometriosis was increased, and the levels of the pro-inflammatory factors IL-1β, IL-18 and TGF-β are increased." (PMID 38938880, 2024). "Specifically, the levels of TNFα, IL-1β, and IL-6 are increased in peritoneal macrophages isolated from endometriosis patients." (PMID 39192982, 2024). "This case report highlights the intra-individual heterogeneity in nerve bundle density and NGF and IL-1β expression between anatomic subtypes of endometriosis in patients with greater disease burden." (PMID 38785989, 2024). "SASP gene products identified by RNAseq include many inflammatory biomarkers that have been historically analyzed in endometriosis, including IL-1β, IL-6, IL-8, CCL5, TNF-α, CCL2, MMP3, HMGB1, p16, and p21." (PMID 38879630, 2024). "Elevated TNFα, IL-1β, and IL-6 levels have been reported in the blood, peritoneal fluids, and/or eutopic and ectopic endometrial tissues of women with endometriosis." (PMID 39192982, 2024).
endometriosis (continued). "MMP10, PAEP and IL1B revealed low expression in endometriosis, while showing a positive staining in positive control tissue, and are therefore not considered potential for further research." (PMID 39373851, 2024). "Endometriosis induces systemic inflammation through pro-inflammatory cytokines such as IL-1β, IL-6, and TNF-α." (PMID 39381444, 2024). "In agreement with our findings, Grandi and co-workers reported that exposure to inflammatory cytokines TNFα and IL1β reduced the expression of PR mRNA and protein expression in the endometrial stromal cells of women with endometriosis." (PMID 37260554, 2023). "The concentration and activity of IL-1β were reported to be increased in the peritoneal fluid, serum, and endometriotic lesions of women with endometriosis." (PMID 37893241, 2023). "Inflammation in endometriosis is driven by elevated levels of macrophages and cytokines, including interleukins (IL-1β, IL-6, IL-8, IL-17), tumor necrosis factor α (TNFα), cyclooxygenase 2 (COX-2), and macrophage inhibitory factor (MIF)." (PMID 37834449, 2023). "In patients with endometriosis, the upregulation of miRNA 125b-5p and downregulation of let 7b-5p have been associated with increased proinflammatory cytokines such as TNF-α, IL-1β, and IL-6." (PMID 37834449, 2023). "The ability of mast cells to produce IL-1β has also been demonstrated in a model of endometriosis, in which estrogen-stimulated mast cells can produce IL-1β via K+ efflux." (PMID 37564649, 2023). "Curcumin was also found to repress activation of NF-κB induced by TNF-α and IL-1β in endometriosis, with effects such as reduced production of proinflammatory cytokines, chemokines, and cell adhesion molecules." (PMID 36769226, 2023). "It has been suggested that NLRP3 inflammasome, which leads to the activation of IL-1β, contributes to the progression of endometriosis." (PMID 36982152, 2023). "Here, we demonstrated that endometriosis in rats caused the activation of NLRP3 and NF-κB pathways as well as the increase in levels of IL-1β and TNF-α, while fisetin inhibited the activation of NLRP3/NF-κB as well as diminished the levels of IL-1β and TNF-α." (PMID 36982152, 2023). "On molecular level, both suture and inoculation models of endometriosis induced a pro-inflammatory state with increased concentrations of pro-inflammatory cytokines IL-1β and/or TNF-α." (PMID 36844654, 2023). "There are increased levels of pro-inflammatory cytokines, such as TNF-α, IL-1β, IL-6, and IL-17A, in the PF and ectopic lesions of patients with endometriosis, promoting the inflammation and development of endometriosis." (PMID 36865552, 2023). "IL-1β, IL-6, and IL-15 expressions were lower, and IL-4 was higher in endometriosis lesions compared to that in eutopic endometrium in the proliferative phase." (PMID 35269619, 2022). "Recently, IL-1β has been implicated to induce the production of proinflammatory cytokines, including IL-6 and IL-8, by increasing TDO2 expression in endometriosis." (PMID 35733134, 2022). "SR-16234 can suppress the expression of genes associated with inflammation in endometriosis-like lesions, such as TNF-α and IL-1β, preventing the growth and proliferation of endometriotic tissues." (PMID 35885010, 2022). "Several cytokines are elevated in the peritoneal fluid and in the serum of patients with endometriosis; however, the cytokines IL-1β, TNF-α, IL-6, and IL-10 play a fundamental role in the pathogenesis of endometriosis." (PMID 35807280, 2022). "Recombinant human TNF binding protein 1, the activation of α-7 nicotinic acetylcholine receptors (nAChR), and the suppression of LPS-induced IL-1β mRNA expression have also been reported to be potentially effective endometriosis treatments." (PMID 36555618, 2022). "The involvement of IL-1β in endometriosis has been studied, and research on the treatment of endometriosis using IL-1β receptor antibodies has been reported." (PMID 35351143, 2022).
endometriosis (continued). "The inflammatory cytokines, TNF-α and IL-1β, play crucial roles in triggering the inflammatory pathway and are upregulated in the peritoneal fluid of women with endometriosis." (PMID 36428561, 2022). "In a recent study, the researchers found that treatment with anti-bone morphogenetic protein 1 (anti-BMP1) antibodies dose-dependently increased lesion volume in mice with endometriosis, reduced IL-17 and IL-1β levels." (PMID 35582411, 2022). "PGE2 is an eicosanoid produced by cyclooxygenase (COX)-2, and increased expression of COX-2 in endometriotic lesions plays a role in the evolution of the disease, while IL-1β regulates COX-2 expression in endometriosis." (PMID 36359004, 2022). "We also measured peritoneal concentrations of IL-1β, as this cytokine was reported to be elevated in the peritoneal fluid of women with endometriosis." (PMID 35433736, 2022). "The aim of this study was to investigate the association of TNF-α (G-308 A), IL-1β (C+3954T) and IL1-Ra intron 2 VNTR polymorphisms with the risk of endometriosis in Mexican mestizo women." (PMID 36028805, 2022). "In lesions, we observed higher expression of p16Ink4a and IL-1β and lower expression of lamin b1 than in the eutopic endometrium, which indicates that senescent cell biomarkers are present in endometriosis lesions." (PMID 35269619, 2022). "Laboratory studies have shown that peritoneal macrophages in women with endometriosis express cytokines IL-6, IL-1B, and tumor necrosis factor more than in women with benign abnormalities." (PMID 36381357, 2022). "The results show that treatment SR-16234 significantly reduced the level of proinflammatory cytokines, namely TNF-α and IL-1β, in the endometriosis-like lesions." (PMID 35885010, 2022). "In this study, we investigated the association of TNF-α (G-308A), IL-1β (C+3954T) and IL-1Ra (intron 2, VNTR) polymorphisms and endometriosis in Mexican mestizo women from Mexico City and its surroundings." (PMID 36028805, 2022). "The latest study also demonstrated the role of NLRP3/caspase-1/IL-1β-mediated pyroptotic pathway in endometriosis." (PMID 36354688, 2022). "Previous studies have demonstrated that the levels of pro-inflammatory cytokines IL-6, TNF-α, IL-1β, and IL-17 in the localized lesion (ectopic endometrium and peritoneal cavity) and circulation (serum) were significantly increased in women with endometriosis." (PMID 33815277, 2021). "In this study, significantly higher serum IL-1β concentrations were observed in the endometriosis group, particularly in stage IV, when compared with the control group of healthy women." (PMID 33669013, 2021). "Taken together, our study provided mechanistic evidence of how estrogen can promote MC-derived NLRP3 inflammasome activation and IL-1β secretion, which lead to the development of endometriosis." (PMID 34630429, 2021). "Increased activation of macrophages in peritoneal fluid in patients with endometriosis leads to the upregulation of proinflammatory factors, such as IL-1β, IL-6, IL-8, and TNF-α, which create favorable conditions for their occurrence." (PMID 33574880, 2021). "Serum IL-1β levels were significantly higher in women with deep infiltrating endometriosis than in normal women in the control group." (PMID 33906696, 2021). "Many authors reported high levels of pro-inflammatory cytokines (e.g., IL-1β and IL-6 in pelvic fluid in women with endometriosis compared to the control group), which indicates a significant role for immune markers in the pathogenesis of endometriosis." (PMID 33669013, 2021). "Accumulating evidence suggests that IL-1β plays an important role in the development of endometriosis." (PMID 33906696, 2021). "In mice with endometriosis, the lesions were reduced in size and pain was relieved with significantly lower IL-1β levels following the use of NF-κB activation inhibitors such as norethindrone." (PMID 33906696, 2021).